DDX3X (DEAD-box helicase 3 X-linked)
Diseases named in the same sentence as DDX3X in open-access papers (continued):
Sharing a sentence is not in itself a finding about the gene and the disease.
lymphoma (11 papers, 2019 to 2025). A malignant (clonal) proliferation of B- lymphocytes or T- lymphocytes which involves the lymph nodes, bone marrow and/or extranodal sites. "An examination of an extensive collection of clinical specimens from lymphoma patients indicated that mutations in Ddx3X (R475 and R534), predominantly found in the MHG DLBCL subtype and also observed in medulloblastoma, negate the helicase activity." (PMID 38993792, 2024). "Since the patients with double‐hit and triple‐hit lymphomas were excluded from this study, it was speculated that identifying the DDX3X mutations at the time of relapse might be valuable for evaluating the prognosis of rrDLBCL patients." (PMID 36971051, 2023). "The same study also found that cell lines with DDX3X mutations or DDX3X knockdown enhances the proliferation and their migratory potential of lymphoma cells lines, whereas overexpression of an unmutated DDX3X decreased proliferation." (PMID 37035206, 2023). "Since it is known that alteration of MYC alone cannot induce a lymphoma and rely on other genetic alterations, DDX3X is a good candidate to investigate." (PMID 37035206, 2023). "Negative posttranscriptional regulation offers a unifying explanation for the following observations: 1) In DDX3X-mutant lymphomas in human males, Gong and colleagues reported that DDX3Y transcript levels were elevated compared to wild-type lymphocytes (B cells)." (PMID 39026797, 2024). "This provides an explanation why DDX3X mutations in human B cells are not selected in female GC-derived lymphoma." (PMID 37035206, 2023). "However, patients with a loss of DDX3Y – i.e male patients whose cancer cells have lost their Y chromosome – carry lymphoma cells relying only on the DDX3X paralog." (PMID 37035206, 2023). "It is also likely that DDX3X inhibitors would be more effective in combination with other established lymphoma drugs such as cyclophosphamide, etoposide, doxorubicine and others, allowing to reduce their dosage and thereby overall toxicity and enhancing their effectiveness." (PMID 37035206, 2023). "An additional study even estimates that 28% of DLBCL associated with altered MYC expression harbor DDX3X mutations that are particularly enriched in tumors defined as single-hit lymphoma (MYC but no other rearrangements) and c-MYC cluster-amplified lymphoma." (PMID 37035206, 2023). "Conversely, in lymphoma patients harboring a DDX3X mutation, selective inhibition of DDX3Y without affecting DDX3X would be extremely advantageous as it would target only lymphoma cells relying on DDX3Y." (PMID 37035206, 2023). "Loss of DDX3X function prevents MYC oncogene-driven lymphomagenesis by moderating global protein synthesis and buffering MYC-induced proteotoxic stress, but established male lymphoma cells can overcome this effect by aberrantly upregulating DDX3Y protein levels." (PMID 39975375, 2025). "At present, the characteristics of DDX3X in lymphoma are still very mysterious and have not been fully revealed." (PMID 36971051, 2023). "DDX3 being an essential gene, at least one of the two paralogs is indispensable for cell survival, particularly in a B cell lymphoma context as shown by the aberrant DDX3Y expression in human lymphoma with a DDX3X LOF; and by the DDX3Y overexpression in murine lymphoma cells with a Ddx3x KO." (PMID 37035206, 2023).
glioblastoma (10 papers, 2015 to 2025). The most malignant astrocytic tumor (WHO grade IV). "This study represents the first demonstration that DDX3X-targeted small molecules are feasible and promising drugs also in glioblastoma." (PMID 34771731, 2021). "DDX3X also elicited a Snail repression-dependent glioblastoma migration." (PMID 32326089, 2020). "We further measured the expression of DDX3X in different cell subtypes within the tumor by performing single-nuclear RNA-Seq (snRNA-Seq) for 6 cases of glioblastoma (GBM, the most malignant glioma, WHO IV grade)." (PMID 37988165, 2023). "In the specific case of glioblastomas, these authors found proof of biallelic expression in females of KDM6A (encodes the lysine-specific demethylase 6A), KDM5C (encodes the lysine demethylase 5C), DDX3X (encodes a DEAD-box helicase 3 X-linked), and ATRX (encodes the ATRX chromatin remodeler)." (PMID 33752729, 2021). "Interestingly, a positive correlation between DDX3X levels and Snail expression was observed in 31 patients with glioblastoma multiforme (GBM), which is an aggressive and malignant primary brain tumor that is characterized by poor survival rates." (PMID 34771731, 2021).
liver cancer (8 papers, 2015 to 2023). An epithelial or non-epithelial malignant neoplasm that arises from the liver. "An exploration of transcriptomic data from 373 liver cancer patients from The Cancer Genome Atlas (TCGA) using Ingenuity Pathway Analysis (IPA) suggested an association between DDX3X expression and cancer metastasis." (PMID 37371098, 2023). "In liver cancer, the reduction in DDX3X is positively linked with hepatitis virus infection, especially HBV." (PMID 33627125, 2021). "The molecular mechanism regarding ATP-dependent RNA helicase DDX3X in liver cancer progression had been addressed in many studies." (PMID 37371098, 2023). "In liver cancer, well-differentiated cell lines showed higher expression of DDX3X than did poorly differentiated cell lines." (PMID 33627125, 2021). "Overexpression of DDX3X in the liver cancer cell line Tong leads to moderate colony formation in soft agar, whereas unadulterated Tong cells per se do not have this ability." (PMID 33627125, 2021). "In liver cancer, DDX3X affects the levels of a subset of tumour-suppressive miRNAs by reducing DNMT3A (DNA methyltransferase 3A) binding and hypermethylation on the promoter regions of these miRNAs." (PMID 33627125, 2021). "In liver cancer, DDX3X inhibits the eIF4E-eIF4G interaction by binding with eIF4E to repress global protein synthesis." (PMID 33627125, 2021). "Relevant evidence has revealed DDX3X upregulation in diosgenin-inhibited cell migration and invasion in two liver cancer cell lines, HepG2 and SMMC-7721, along with alterations in the expression of the metastasis-related biomarkers β-catenin and E-cadherin." (PMID 31906196, 2019). "Depletion of DDX3X expression in liver cancer cells HepG2 increased cell migration ability, and the phenotype was reversed upon restoration of tumor-suppressive miR-200b, miR-200c, miR-122, and miR-145, respectively." (PMID 31906196, 2019). "The experimental findings indicated that ATP-dependent RNA helicase DDX3X might potentially possess functions in regulating liver cancer progression." (PMID 37371098, 2023). "Investigating the interplay of DDX3X with PABPC1 could better explain the role of DDX3X in liver cancer as well as define its implication in ovarian cancer." (PMID 35954483, 2022). "However, reduction of DDX3X was further reported to induce self-renewal capability and co-expression of stemness gene signature in liver cancer." (PMID 31906196, 2019). "Hence, the transcriptomic data indicate the possibility that high DDX3X expression in liver cancer patients might trigger cancer progression, especially via metastasis, consistent with the observation of poor clinical outcomes." (PMID 37371098, 2023). "Moreover, DDX3X represses the expression of signature stemness genes, including NANOG, OCT4, c-MYC, SOX2, KLF4, BMI1 and CK19, to prevent the generation of CSCs in liver cancer." (PMID 33627125, 2021).
pancreatic cancer (8 papers, 2019 to 2025). "Overall, our findings suggest that DDX3X promotes migration and invasion through EMT in vitro and that the expression of DDX3X is closely linked to vimentin-mediated progression in pancreatic cancer." (PMID 38316768, 2024). "Therefore, we endeavored to elucidate the underlying regulatory mechanism of SIRT7 by DDX3X in pancreatic cancer." (PMID 38316768, 2024). "For instance, DDX3X acts as an oncogenic gene in pancreatic cancer, regulating either transcription or translation pathways to promote tumor progression." (PMID 40885716, 2025). "In summary, our findings suggest that DDX3X promotes cell proliferation in vitro in pancreatic cancer." (PMID 38316768, 2024). "The results of our study indicate a positive relationship between SIRT7 mRNA and DDX3X mRNA in pancreatic cancer patient specimens." (PMID 38316768, 2024). "Our approach involved the use of lentiviral short-hairpin RNA (shRNA) to stably silence DDX3X expression in a variety of pancreatic cancer cell lines, namely, MIA PaCa-2, PANC-1, SW1990, AsPC-1, and CFPAC-1." (PMID 38316768, 2024). "Depletion of Kindlin-2 in pancreatic cancer cells markedly decreased DDX3X-mediated c-Myc mRNA translation, reprogrammed glucose metabolism, and thereby inhibited cell proliferation in vitro." (PMID 37649609, 2023). "Consistently, it was found that AEP specifically cleaved DDX3X in response to hypoxia and nutrient deprivation in pancreatic cancer cells (PANC-1) and osteosarcoma cells (143B)." (PMID 37988165, 2023). "The obtained outcomes present a strong indication of a strong positive correlation between PD-L1 expression and DDX3X, which signifies the potential of DDX3X as a reliable marker for diagnosis and prognosis and treatment response prediction in pancreatic cancer." (PMID 38316768, 2024). "Additionally, the messenger RNA (mRNA) and protein levels of DDX3X were significantly higher in nine diverse cell lines of human pancreatic cancer than in normal human pancreatic ductal epithelium (HPDE) cells." (PMID 38316768, 2024). "In light of these discoveries, one hypothesis suggests that the upregulation of DDX3X is a contributing factor to the advancement and dissemination of pancreatic carcinoma." (PMID 38316768, 2024). "The results demonstrated that DDX3X overexpression could promote pancreatic cancer growth in vivo." (PMID 38316768, 2024). "In light of the identification of DDX3X as an unfavorable prognostic biomarker in PDAC, we undertook an investigation of its specific role in pancreatic cancer." (PMID 38316768, 2024). "Another study also reported elevated miR-2355-3p enhanced AK4 expression, and miR-2355-3p/DDX3X/AK4 axis was involved in proliferation and invasion of pancreatic cancer cells." (PMID 35611768, 2022). "In vivo analyses of pancreatic tumors from human and murine PDAC samples demonstrated colocalization of DDX3X and SIRT7, suggesting that SIRT7 may be subject to DDX3X regulation." (PMID 38316768, 2024).
diffuse large B-cell lymphoma (7 papers, 2019 to 2025). "Recurrent DDX3X mutations in diffuse large B-cell lymphoma (DLBCL) are associated with worse clinical outcomes." (PMID 35874614, 2022). "In a study published in 2019, a class of molecular high-grade diffuse large B-cell lymphoma (MHG) was defined, which had significantly higher mutation frequencies than GCB in KMT2D, BCL2, MYC, or DDX3X." (PMID 34925435, 2021). "Additionally, note that the lower DDX3X levels were displayed in uveal melanoma, diffuse large B-cell lymphoma, thymoma, liver hepatocellular carcinoma, kidney papillary cell carcinoma, and skin cutaneous melanoma, which indicates that DDX3X might has a dual role in cancer progression." (PMID 31906196, 2019).
oral cancer (7 papers, 2014 to 2025). "As described by Shigeishi (2023), in HPV-positive oral cancers, mutations in the PIK3CA gene are frequently observed, while there are somatic mutations in ZNF750, FGFR3, DDX3X, CASZ1, PTEN, and CYLD, differentiating them from HPV-negative oral cancers." (PMID 40284955, 2025). "It targets DDX3X in oral cancer, inducing cancer cell death and downregulating DDX3X expression." (PMID 38539466, 2024).
oral squamous cell carcinoma (7 papers, 2015 to 2025). "DDX3X CNVs (copy number variants) were also found in patients with oral squamous cell carcinoma (OSCC)." (PMID 33627125, 2021). "Our analysis identified the specific interaction of DDX3X with different members of the KRT family involved in oral squamous cell carcinoma (OSCC) proliferation, such as KRT5, KRT14 and KRT17." (PMID 35954483, 2022). "Treatment of doxorubicin in oral squamous cell carcinoma H357 cells showed the decrease in inorganic phosphate (Pi) release, ATP hydrolysis, DDX3X downregulation, and the anticancer activity, which was evaluated by MTT method." (PMID 31906196, 2019). "A clear mechanism that explains the roles of DDX3X in oral squamous cell carcinoma (OSCC) has not been elucidated yet." (PMID 35954483, 2022). "Furthermore, DDX3X specifically increases the binding of the cap-binding complex (CBC) to the uORF of ATF4 mRNA, which leads to the recruitment of eIF3 and facilitates translation in oral squamous cell carcinoma cell invasion and metastasis." (PMID 31906196, 2019).
ovarian carcinoma (7 papers, 2015 to 2023). A malignant neoplasm originating from the surface ovarian epithelium. "We show that PHGDH is upregulated at the translational level in cisplatin resistant ovarian cancer cells, which is regulated by recruitment of DDX3X on the PHGDH transcript." (PMID 34178629, 2021). "The current study found that long non-coding RNA (Lnc RNA) RPRM was upregulated in cisplatin-resistant ovarian cancer cells and promoted enrichment of DDX3X on the PHGDH mRNA." (PMID 34178629, 2021). "However, DDX3X appeared to be an unfavorable prognostic biomarker in liver, pancreatic, breast and ovarian cancer." (PMID 37371098, 2023). "Importantly, knockdown of DDX3X significantly decreased PHGDH expression in cisplatin-resistant ovarian cancer cells." (PMID 34178629, 2021). "DDX3X expression was not different, while its enrichment on the PHGDH mRNA was increased, indicating that other factor(s) might guide DDX3X to the PHGDH mRNA in platin-resistant ovarian cancer." (PMID 34178629, 2021). "Therefore, is possible that DDX3X exerts an oncosuppressive role in ovarian cancer by acting on the negative regulation of NFκB2 at different levels by direct interaction with NF-κB or by enhancing the expression of ISG15 that in turn suppresses NFκB2 activity." (PMID 35954483, 2022). "In our recent study, we found that PHGDH was upregulated in epithelial ovarian cancer and was regulated by lncRNA RMRP and DDX3X in translational level." (PMID 36105480, 2022). "Thereby, our findings identified cooperation of DDX3X and RPRM to promote translation of PHGDH transcript in cisplatin-resistant ovarian cancer cells." (PMID 34178629, 2021). "Among DDX3X unique interactors, we identified ISG15 (interferon-stimulated gene 15), which in ovarian cancer is involved in tumor suppression by decreasing the expression levels of phospho-ERK1 and ERK downstream genes that are associated with cancer progression." (PMID 35954483, 2022). "The current study found that although total DDX3X expression was not distinct between cisplatin-sensitive and cisplatin-resistant ovarian cancer cells, while its recruitment on PHGDH mRNA was augmented in cisplatin-resistant ovarian cancer cells." (PMID 34178629, 2021). "Besides miRNA biogenesis regulation, the role of DDX3X ovarian cancer has not been defined yet." (PMID 35954483, 2022).
pancreatic ductal adenocarcinoma (7 papers, 2019 to 2024). An infiltrating adenocarcinoma that arises from the epithelial cells of the pancreas. "Reportedly, DDX3X induces epithelial-mesenchymal transition in pancreatic ductal adenocarcinoma by promoting SQSTM1 accumulation, indicating the interaction between DDX3X and SQSTM1." (PMID 38265972, 2024). "The investigation revealed a significant correlation between high DDX3X expression in pancreatic ductal adenocarcinoma (PDAC) tissues and cells and an unfavorable prognosis for PDAC patients." (PMID 38316768, 2024). "Overexpression of DDX3X is a poor prognosis marker in gallbaldder carcinoma and pancreatic ductal ccarcinoma and in pancreatic ductal carcinoma, DDX3X promotes p62 accumulation that in turn facilitates epithelial–mesenchymal transition and metastasis." (PMID 35954483, 2022). "In a cohort of 106 pancreatic ductal adenocarcinomas (PDAC), high CD112 and DDX3 (DEAD-box helicase 3 X-linked) expression levels were associated with poor prognosis and progression." (PMID 34507594, 2021). "In addition, DDX3X has been shown to promote sequestosome 1 (SQSTM1/p62) accumulation in pancreatic ductal adenocarcinoma, suggesting a regulatory relationship between DDX3X and SQSTM1." (PMID 38265972, 2024). "The precise mechanisms through which DDX3X regulates SIRT7 expression in human pancreatic ductal adenocarcinoma (PDAC) cells have not been previously reported." (PMID 38316768, 2024).
/T-cell lymphoma (6 papers, 2016 to 2024). "Recurrent mutations of DDX3X are also found in Natural killer (NK)/T-cell lymphoma (NKTCL), with a positive correlation between DDX3X mutations and poor clinical outcome." (PMID 35874614, 2022). "DDX3X mutations are normally present in NK/T-cell lymphoma and are correlated with a poor clinical outcome." (PMID 35954483, 2022). "Of note, DDX3X encodes an RNA-helicase and contains frequently inactivating mutations in NK/T-cell lymphoma patients." (PMID 28977998, 2017). "This function could be similar to that already reported in NK/T-cell lymphoma where a loss of DDX3X was associated with a higher expression of NF-κB." (PMID 35954483, 2022). "Whereas, the mutant spectrum of DDX3X in DLBCL was dissimilar to that in natural killer/T-cell lymphoma and chronic lymphocytic leukemia, in which mostly truncating mutations (nonsense, frameshift or splice site) have been identified." (PMID 38609996, 2024).
B cell lymphomas (6 papers, 2022 to 2025). "First, DDX3X mutations occur with high frequency particularly in those GC-derived B-cell lymphomas that also show translocations of the c-MYC proto-oncogene, which occurs in almost all BL and a subset of DLBCL." (PMID 37035206, 2023). "The recent discovery of the aberrant expression of DDX3Y compensating the loss of DDX3X function in tumors with c-MYC activation has opened a new area for developing new therapeutic strategies for B cell lymphomas." (PMID 37035206, 2023). "However, full lymphomagenesis requires DDX3 activity since an upregulation of DDX3Y expression is invariably found in GC derived B-cell lymphoma with DDX3X LOF mutation." (PMID 37035206, 2023). "Moreover, given that a pharmacological inhibition of c-MYC is difficult, inhibition of DDX3X or DDX3Y could represent alternative therapeutic avenues for the treatment B-cell lymphoma in male patients with DDX3X LOF mutations." (PMID 37035206, 2023). "The observation that co-treatment with BSO, which depletes glutathione, significantly enhanced RK-33 cytotoxicity suggests a potential therapeutic strategy that exploits oxidative stress to maximize the impact of DDX3X inhibition in B-cell lymphoma." (PMID 40772229, 2025). "However, one observation that remained coherent between the two studies is that both models, male BL patients and male mice with immature B cell lymphoma, show respectively aberrant and high DDX3Y expression that compensates for the loss of DDX3X." (PMID 37035206, 2023). "However, DDX3X LOF mutations are frequent in human BL but never seen in murine B-cell lymphoma modeling BL." (PMID 37035206, 2023).